CD4 (CD4 molecule)
Diseases named in the same sentence as CD4 in open-access papers (continued):
Sharing a sentence is not in itself a finding about the gene and the disease.
candidiasis (continued). "CD4+ T cells and innate lymphoid cells play a protective role in invasive candidiasis, and the reduction in lymphocytes in patients with COVID‐19 may induce Candida invasion and colonization, while Candida can destroy immune cells, induce inflammatory responses, and aggravate COVID‐19 progression." (PMID 37119437, 2023). "Our studies on CD4 T-cell depletion, which show the abrogation of the protective effect of the CAF01 Als3p/Hy1p vaccine in both models of Candida infection, confirm the importance of cell-mediated immunity." (PMID 40951285, 2025). "The host’s main defense against Candida species is cell-mediated immunity, and CD4+ T helper cells and CD8+ cytotoxic T-cells are the main players in preventing invasive candidiasis." (PMID 38404288, 2024). "Cell-mediated adaptive immune responses constitute the mainstay of host defense mechanisms against systemic candidiasis, wherein both CD4+ T helper cells and CD8+ cytotoxic T-cells are the predominant players involved in controlling Candida infection." (PMID 34696267, 2021). "For mice with severe invasive candidiasis, expression of LC3B and p62/SQSTM1 was higher in CD4+ T-cell-specific mTOR knockout mice but lower in CD4+ T-cell-specific TSC1 knockout mice compared with wild-type mice." (PMID 31668132, 2019). "Most interestingly, there was a significant difference in mortality between CD4+ T-cell-specific mTOR knockout and TSC1 knockout mice and wild-type mice with severe invasive candidiasis." (PMID 31668132, 2019). "In the post-ART period the median CD4 T cell count at the time of a candida diagnosis was 368 cells/mm3 (IQR 222–309 cells/mm3), and the median time from ART initiation to a diagnosis of candidiasis was 554 days (IQR 172–753 days)." (PMID 26930571, 2016). "Although CD4+ T-cells do not have direct cytolytic activity, they still play a critical role against Candida infection." (PMID 34696267, 2021). "In our knowledge, HIV+ patients with CP have been studied without considering Candida infection, nor the clinical conditions of the patients, such as CD4+ T cell count and HAART." (PMID 31316513, 2019). "This was found to be significantly lower than the mean CD4 counts of 32 patients without Candida infection (412.3 cells/μL; range of 256–583 cells/μL and standard deviation of 93; p value < 0.05)." (PMID 27092278, 2016). "It was later recognized that IL-12 shares the p40 subunit with IL-23, which promotes the differentiation of Th17 subset of CD4 T cells, suggesting a role for Th17, but not Th1, response in protection against candidiasis." (PMID 27280548, 2016). "Actually, the relationship between candidiasis and CD4 cells is not direct." (PMID 37545607, 2023). "In contrast, CHC tissues had higher proportions of both T helper (CD4+) and cytotoxic T cells (CD8+) in the lamina propria compared with squamous papilloma, suggesting that the host immune response differed between the conditions and was likely dependent on Candida infection." (PMID 31718115, 2019). "Like Dectin-1, Dectin-2 has been shown to have a non-redundant role during systemic candidiasis in vivo, so we assessed whether absence of this receptor would also affect CD4+ T-cell responses during infection." (PMID 26349660, 2016). "Although a recent study from Uganda showed that giving fluconazole prophylaxis to those with a CD4 count <200 cells/mm3 can further reduce the impact of candidiasis both pre and post ART, it did not reduce overall mortality, and is currently not recommended by WHO." (PMID 23284857, 2012). "The France-based ANSR-106 study, which used a 2-month on/2-month off treatment strategy, did not result in clinical endpoint differences between arms (CD4+ T cell count >300 cells/μl), but the interrupting arm had higher frequency of lymphadenitis and candidiasis." (PMID 21738668, 2011). "However, neither plasma HIV-RNA, gender, age, candidiasis and HCV infection could explain the association between IDU and CD4 cell decline." (PMID 24388495, 2014).
candidiasis (continued). "Results from the CD4-driven STACCATO study, with re-treatment threshold of CD4+ T cell count <350 cells/μl, suggest that higher CD4+ thresholds may minimize the risks of interrupting ART, although even in that study the interrupting ARM had higher frequency of candidiasis." (PMID 21738668, 2011).
chronic kidney disease (70 papers, 2012 to 2025). Impairment of the renal function secondary to chronic kidney damage persisting for three or more months. "Key predictors, including higher APACHE II scores, longer durations of intravenous corticosteroid use, elevated CMV IgG titers, lower CD4+ lymphocyte counts, and histories of chronic kidney disease or organ transplantation, were associated with increased predicted probabilities of CMV reactivation." (PMID 41430129, 2025). "Multivariate Cox regression analysis revealed that a higher intensity of interstitial CD4+ T cell deposition remained as an independent predictor of the double endpoint with doubling of baseline serum creatinine or end-stage renal disease." (PMID 39654881, 2024). "The ninth individual was an unvaccinated 69-year-old Latin American man with a CD4+ cell count below 500 cells/μl with chronic renal failure due to HIV-related nephropathy." (PMID 37199566, 2023). "Our analysis revealed that the presence of chronic kidney disease, the nadir CD4 lymphocyte count, the peak viral load, and the age at HIV diagnosis were all crucial factors to include in the assessment." (PMID 36831190, 2023). "Good vaccine responses would be expected for patients with chronic kidney disease, human immunodeficiency virus infection with normal CD4 counts, immune-mediated inflammatory diseases, post-splenectomy states, and solid tumors." (PMID 35632555, 2022). "Good vaccine responses would be expected for patients with chronic kidney disease, human immunodeficiency virus infection (normal CD4 counts), immune-mediated inflammatory diseases, post-splenectomy states, and solid tumors." (PMID 35632555, 2022). "Another report confirmed this age associated rise in CD4+ T cell DUSP6 expression, and found that young immunosuppressed patients with end stage renal disease have DUSP6 levels comparable to elderly healthy individuals." (PMID 30941033, 2019). "The predictive value of histological lesion, baseline CD4 cell count and viral load for end-stage renal disease (ESRD) or death were determined using the Cox regression model." (PMID 27007656, 2016). "A study found the CD4 T regulatory cells worsen chronic kidney disease (CKD) or end-stage kidney disease (ESKD), suggested that CD4 T regulatory cells might also promote the progression of ADPKD." (PMID 35847973, 2022). "Specifically, in elderly patients with chronic renal failure the expansion of CD4posCD28null T cells which normally comprise <1% of the CD4 T cell population may be such that over 50% of CD4 T cells become CD28null." (PMID 33937299, 2021). "Similarly, tertiary lymphoid structures enriched in PD-1+ CD4+ T cells are observed in chronic kidney disease developed in aged mice and in humans." (PMID 33679735, 2021). "Most patients in the Nephrology Department had chronic kidney diseases, leading to a range of immune system defects such as decreased chemotaxis and phagocytosis of monocyte/macrophage, B-cell lymphopenia, and depressed CD4+ and CD8+ T cell responses." (PMID 33213361, 2020). "Moreover, we previously demonstrated strong correlations between TREC content in CD4+ T cells and frequencies of CD31+CD4+ T cells in end-stage renal disease patients." (PMID 32903778, 2020). "Proinflammatory CD4+ T cells without the costimulatory molecule CD28 (CD4+CD28null T cells) are expanded in patients with end-stage renal disease (ESRD) and associated with atherosclerotic vascular events (AVE)." (PMID 24288592, 2013). "Similarly, patients with chronic kidney disease often have CD4+ Treg dysfunction." (PMID 40612664, 2025). "The variables selected included APACHE II score, CMV IgG level, history of organ transplantation, chronic kidney disease (CKD), CD4+ lymphocyte count, and the number of days of intravenous corticosteroid use within 28 days." (PMID 41430129, 2025). "Patients with chronic kidney disease (CKD) exhibit an expansion in the circulating CD4+CD28null cell population." (PMID 24347824, 2013).
chronic kidney disease (continued). "Chronic kidney disease (CKD) patients have lower percentages of peripheral T lymphocytes, both CD4+ and CD8+, and B lymphocytes in the blood." (PMID 23800151, 2013). "However, in patients with end-stage renal disease the numbers of circulating CD4+CD28null T cells may increase considerably and may represent >50% of the total CD4+ T cell population." (PMID 24288592, 2013). "A reduction in CD28 expression both in CD4 and CD8 subpopulations was also found in patients with end stage renal disease." (PMID 36320075, 2022). "Accordingly, recent studies and a meta-analysis have suggested that end-stage renal disease (ESRD) and RRT influence immunity by lowering CD4+ lymphocytes and Tregs." (PMID 35109826, 2022). "We observed that end-stage renal disease and dialysis resulted in a decrease of CD8+ T, B, and NK cells in contrast to T and CD4+ T lymphocyte counts resembling that of healthy volunteers." (PMID 30729139, 2019). "The outcomes of chronic kidney disease (CKD) and ESRD or death were evaluated by baseline CD4 cell count." (PMID 27007656, 2016). "Comparative transcriptome profiling analysis of non-renal and end-stage renal disease (ESRD) phenotypes of SLE was performed using CD4 + and CD8 + cDNA microarrays of sorted T cells." (PMID 38650001, 2024). "Another important aspect of management is control of underlying immunocompromised states, for example, strict glycaemic control for diabetics, low viral load, and high CD4 counts for patients with HIV and stable optimised renal function for those with chronic kidney disease." (PMID 33204559, 2020). "The drug withdrawal group had higher APACHE-II score (median [interquartile range]: 21 vs. 17 points), higher CD4%, lower hemoglobin level, higher rates of chronic obstructive pulmonary disease (COPD) and chronic renal failure, and lower rate of extrapulmonary tuberculosis (P < 0.05)." (PMID 30717702, 2019). "Older age, overall comorbidities, low CD4 T-cell count, and non-tenofovir ART were associated with higher rates of oxygen requirement in the first model, but further adjustment mainly by chronic kidney disease showed no impact of tenofovir therapy in this outcome (model 2)." (PMID 37243213, 2023). "However, the relationship of CD4/CD8 ratio recovery and chronic kidney disease (CKD), and whether cumulative antiretroviral therapy (ART) is effective in the CD4/CD8 ratio recovery and in reducing CKD incidence among HIV patients remain unclear." (PMID 35222339, 2022).
lung disease (70 papers, 2007 to 2026). "Lastly, we studied a cohort of generally young, recently diagnosed PWH with high CD4 + counts at relatively low risk of lung disease." (PMID 36959289, 2023). "An increase in circulating [CD4 + CD25 + Tregs] cells is a hallmark of disturbed immune homeostasis in various pulmonary diseases, including IPF." (PMID 35101101, 2022). "Though none of the ARIP measures were significantly associated with lung disease, CD4 + TN/TM and CD4 + TN had the strongest association (OR = 0.88 and 0.90 respectively) with lung disease." (PMID 35858901, 2022). "It usually only causes diseases in individuals with severely damaged immune system such as HIV patients with extremely low CD4+ T cells, underlying lung disease or sometimes in young children, and chronic obstructive pulmonary disease." (PMID 35283816, 2022). "In the multivariate analysis, corrections were made for underlying lung disease, need for mechanical ventilation, and CD4+ T, CD8+ T, and NK cell counts." (PMID 33985440, 2021). "While the participants enrolled in this study had advanced HIV disease with a median CD4 count of 110 cells/μL, they also represent a young cohort with minimal smoking history who would otherwise be expected to have little underlying pulmonary disease." (PMID 33413293, 2021). "Next, we evaluated the changes in levels of IL-10, a regulatory T cell (CD4 + FoxP3+ T-regs)-associated immunosuppressive cytokine, as T-reg dysfunction is implicated in chronic CF-lung disease pathogenesis." (PMID 29301535, 2018). "Activated CD4+ and CD8+ T cells, CD25+ T cells, and CD4+ CD29+ T cells were all significantly increased in patients with HTLV-1 associated pulmonary disease who had HAM relative to HTLV-1 seronegative patients with pulmonary disease and healthy volunteers." (PMID 33407607, 2021). "The main emphasis of this review focuses on the expression of MHC II on non-professional APCs cell surface and potentially present antigen to CD4+T cells in lung development and different lung diseases." (PMID 39897591, 2025). "CD4+T cells play an important role in lung disease, showing a high degree of heterogeneity and plasticity, and are regulated in response to stimulation with cognate antigens bound to MHC class II molecules." (PMID 39897591, 2025). "Univariate analysis identified age, IgG level below 6.5 g/L, CD4+ T-cell count, CD8+ T-cell count, and pulmonary diseases as significantly associated with the occurrence of IFI (P < 0.05)." (PMID 41081524, 2025). "A positive correlation was found between the severity of lung disease and CD4+ CXCR5+ T lymphocyte levels in patients with SSc (p = 0.01, r = 0.358)." (PMID 38280030, 2024). "Previous work has demonstrated that crosstalk between CD4+ T cells and ILC2s leads to their mutual maintenance, expansion, and cytokine production and plays an important role in the etiology of several lung diseases." (PMID 37646035, 2023). "Here, we review the latest progress on ILC2s and CD4+T cells in the lung, the close relationship between the two, and their relevance in the lung disease and immunity." (PMID 35592688, 2022). "The crosstalk between ILC2s and CD4+T cells, particularly with Th2 cells, plays an important role in a variety of lung diseases." (PMID 35592688, 2022). "Increased CD4+CD25+ T cells and BALF IL-17a correlated with lower oxygen saturations and increased lung permeability, indicative of a potentially pathologic role of certain CD4+CD25+ T cells in the progression of flavorings-related lung disease." (PMID 34941793, 2021). "Here we demonstrated that individuals with treated EPTB maintain higher frequencies of Mtb-reactive CD4+ memory T-cells compared with individuals with prior pulmonary disease or LTBI." (PMID 33391271, 2020). "CD4+ T cells (e.g., Th1, Th2, Th17, and Treg cells) are key participants in the pathogenesis of CS-induced pulmonary disease." (PMID 31379467, 2019).
lung disease (continued). "The CD4/CD8 ratio within the lung has been associated with pulmonary-specific inflammation and lung disease in previous studies." (PMID 28122034, 2017). "This highlights a disease-promoting effect of CD4+CD25+ T cells during the acute phase of BLM-induced lung disease and a protective role of these cells during the fibrotic phase." (PMID 28018357, 2016). "Accordingly, increased IL-4 expression and polymorphism in the IL-4 gene has been correlated with severe RSV lung disease findings consistent with IL-4 mediated differentiation of CD4+ T cells toward Th2-type cells." (PMID 24040360, 2013). "The findings indicate that B6-specific genetic factors influence the expansion of effector/memory CD4+ T cells and Treg cells in advance of the onset of lung disease." (PMID 22171643, 2011). "Conversely, the production of IFN-γ by CD4+ or CD8+ T cells down-regulated the pathological immune mediators in murine experimental models of vaccine-mediated lung-disease exacerbation." (PMID 18335041, 2008). "Although there is growing evidence that CD4+ T cells contribute to various pulmonary disorders, little is known concerning the role of AEC II cells in T cell mediated lung injury." (PMID 17610738, 2007). "Congenic region influence on inbred strain variation in pulmonary CD4% was revealed which, as it may affect radiation induced lung disease, is a potential pre treatment biomarker of radiation response." (PMID 41261392, 2025). "We then established the cross-reactivity of OC43-elicited T cells to SARS-CoV-2 peptides, examined the effect of prior exposure to OC43 on subsequent SARS-CoV-2 infection and lung disease, and determined the contribution of cross-reactive CD4+ T cells to OC43-induced cross-protection." (PMID 38278784, 2024). "In our patient, hematologic malignancies were ruled out and corticosteroids were not routinely used, though underlying lung disease was present in addition to a low CD4 count (920/μl)." (PMID 36212620, 2022). "Here, we will summarize the latest research progress on ILC2s and CD4+T cells in the lung and how their interaction participates in the immune regulation and lung homeostasis and will explore how their dysregulation can lead to lung diseases." (PMID 35592688, 2022). "We hypothesized that the balance of different CD4+CD25+ T cell populations within the lung contribute to the progression of flavoring-related lung disease." (PMID 34941793, 2021). "Secondly, to investigate whether the pulmonary profile of CD4 + Il13+, CD4 + Ifnγ + and CD4 + Il17+ cell numbers at any of the assay times was, collectively, predictive of later lung disease we performed multiple linear regression analyses on these data." (PMID 25889053, 2015). "Patients with severe organ system involvement including neurologic, cardiac, ocular, and advanced pulmonary disease had lower lymphocyte subset counts as a group than those patients with less severe manifestations (CD4 p = 0.0043, CD8 p = 0.026, CD19 p = 0.033)." (PMID 20140091, 2010). "To determine whether the acute response CD4+ cell profile predicted for late stage lung disease, we analyzed the correlation of T helper cell numbers with the fibrosis score and post-irradiation survival time (hereafter survival time) previously documented for these strains of mice." (PMID 25889053, 2015). "The two cases demonstrate distinct spectrums of PJP in PLHIV: one with severe immunosuppression complicated by post-TB lung disease and Pseudomonas infection and the other with PJP arising despite a moderate CD4 count." (PMID 41141140, 2025). "Patients with HP showed a characteristic BAL lymphocytic profile with a predominance of both CD4 and CD8 T lymphocytes, compared to BAL from control patients or patients with other lung diseases." (PMID 41301706, 2025). "Our results demonstrate that prior exposure to OC43 generates cross-protective immunity that is mediated, at least in part, by CD4+ T cells against SARS-CoV-2 infection and lung disease." (PMID 38278784, 2024).